CD36 (CD36 molecule (CD36 blood group))
Diseases named in the same sentence as CD36 in open-access papers (continued):
Sharing a sentence is not in itself a finding about the gene and the disease.
hyperlipidemia (continued). "CD36 signaling contributes to platelet hyperactivity under conditions of hyperlipidemia and chronic inflammation which not only promotes thrombosis, but also facilitates platelet–monocyte interactions." (PMID 35438721, 2022). "Platelet CD36, expressed at 20,000 copies per platelet that recognizes specific oxidized lipid motifs, was found to link hyperlipidemia, oxidant stress, and a prothrombotic phenotype." (PMID 36465448, 2022). "Increases in the surface expression of CD36 are rapid due to roughly 50% of CD36 being stored in the cytosol until recruitment to the membrane for lipid internalization; however, hyperlipidemia in ob/ob mice has been shown to increase CD36 mRNA." (PMID 35269504, 2022). "Compared with the NFD group, the expression of the LPL protein and CD36 protein of the hyperlipidemia rats induced by HFD decreased significantly." (PMID 34681767, 2021). "Excess fatty acids, such as during hyperlipidemia, enter macrophages via cell surface CD36, and CD36 ligands trigger pro-inflammatory macrophage activation and mitochondrial dysfunction." (PMID 33927894, 2021). "In patients with hyperglycemia and/or hyperlipidemia, the CD36 expression is significantly increased in vascular lesions and kidneys compared with control subjects." (PMID 33995128, 2021). "In mouse, hyperlipidemia has been linked to an increased platelet reactivity with proposed roles of oxidized LDL and of the receptor proteins, CD36 and P2Y1216,50–52." (PMID 33293576, 2020). "In summary, we have shown that CD36 expression was increased in kidney tissue of DN patients with hyperlipidemia." (PMID 26000608, 2015). "Specific oxidized phospholipids (oxPCCD36) promote platelet hyper-reactivity and thrombosis in hyperlipidemia via the scavenger receptor CD36, however the signaling pathway(s) induced in platelets by oxPCCD36 are not well defined." (PMID 24400094, 2014). "This is the first study to offer clinical and laboratory evidence of the participation of CD36 in lipotoxicity-induced podocyte FP effacement, suggesting that CD36 could be a therapeutic target for kidney damage accompanied by hyperlipidemia." (PMID 38584832, 2024). "This study provided evidence that hyperlipidemia may promote FP effacement via CD36-mediated lipotoxicity." (PMID 38584832, 2024). "In addition, hyperlipidemia-induced PLT hyperactivity contributes to prothrombosis state development through a CD36-mediated signaling cascade." (PMID 39220644, 2024). "To assess whether localized enrichment of CD36 and LIPG at the LOSS region is associated with elevated lipid metabolism, we exposed mice to acute hyperlipidemia using oral gavage of olive oil." (PMID 39234692, 2024). "summarized that renal CD36 expression is upregulated by hyperlipidemia and hyperglycaemia." (PMID 40625574, 2023). "CD36 facilitates the uptake of triglycerides into brown adipose tissue in response to short‐term cold exposure and contributes to the accelerated plasma clearance of triglycerides in the pathophysiological setting of hyperlipidemia." (PMID 40625574, 2023). "Owing to this functionality, CD36 has been confirmed as a promising candidate to alter the link between myocardial fatty acid utilization and the regulation of the inflammatory response, particularly in hyperlipidemia." (PMID 34881240, 2021). "In hyperlipidemic CD36−/−apoE−/− mice, the absence of CD36 significantly protected the mice from the hyperlipidemia-related prothrombotic phenotype, when compared to hyperlipidemic apoE−/− mice without CD36 deficiency." (PMID 33440673, 2021). "Therefore, it is reasonable to assume that FTO regulates the stability of CD36 mRNA via YTHDF2 dependent on the m6A modification in hyperlipidemia and PA-induced cardiomyocyte inflammation." (PMID 34881240, 2021).
hyperlipidemia (continued). "Palmitic acid-driven upregulation and translocation of CD36 from the cytosol to the plasma membrane lead to an increase in lipid uptake, ROS production and apoptosis in podocytes of patients with diabetic nephropathy and hyperlipidemia." (PMID 28819187, 2017). "However, the specific role of CD36 in podocyte apoptosis in DN with hyperlipidemia remains poorly investigated." (PMID 26000608, 2015). "The aim of the present study was therefore, to investigate the expression of CD36 in kidney tissues from DN patients with hyperlipidemia, and the effect of fatty acid including the mechanism of action on CD36 expression and apoptosis of podocytes using an in vitro model." (PMID 26000608, 2015). "However, the specific role of CD36 in podocyte apoptosis of DN with hyperlipidemia remains poorly investigated." (PMID 26000608, 2015). "CD36 expression was increased in kidney tissue from DN patients with hyperlipidemia." (PMID 26000608, 2015). "Reduction in hyperlipidemia‐induced cardiac damage were observed after luteolin treatment via suppression of lipid deposition (LOX‐1 and CD36) and cardiac fibrosis (MMP2, MMP9, Collagen I, Collagen III, and TGF‐β)." (PMID 39830909, 2025). "Under obese condition, hyperlipidemia and hyperinsulinemia repress RIMKLA to impair BHMT1 activity and elevate Hcy level, which activates AP1 to induce the transcriptions of FASn and CD36, stimulating de novo lipid synthesis and uptake." (PMID 39117631, 2024). "Protein O-GlcNAcylation has not been directly linked to enterocyte physiology but OGT and sOGA activity in other cell types regulate the stability and activity of CD36 and PLIN2, which are central to hyperlipidemia adaptations in the intestine." (PMID 36111295, 2022). "Interestingly, we found that among the four fatty acids uptake relative genes, only fatty acid translocase (FAT)/CD36 was significantly increased in all three animal models, indicating that hyperglycaemia alone or hyperlipidemia alone could increase fatty acids transport into hepatocytes." (PMID 33186123, 2020). "The CD36 expression was analyzed using immunofluorescence staining of kidney tissue samples collected from 20 DN patients with hyperlipidemia and 18 control patients without renal disease." (PMID 26000608, 2015). "Mechanistically, hyperlipidemia induced by HFD feeding acts as the first stimulation for TI via lysoPC stimulation, oxidized low-density lipoprotein (oxLDL) binding to CD36, TLR4 /TLR2 and nucleotide-binding domain, leucine-rich-containing family, pyrin domain-containing 3 (NLRP3) inflammasomes." (PMID 34859106, 2021).
ovarian carcinoma (59 papers, 2013 to 2025). A malignant neoplasm originating from the surface ovarian epithelium. "Driven by cancer-associated adipocytes (CAAs), the upregulation of CD36 in tumor cells facilitates the uptake of FAs in the omental metastasis of ovarian cancer." (PMID 39085485, 2024). "Overexpression of CD36 has been found in several tumors, such as breast and ovarian cancers, and has been associated with poor prognosis." (PMID 35625629, 2022). "Subsequent studies have found that CD36+ cells are associated with a poor prognosis of ovarian cancer, and blocking CD36 can attenuate tumor metastasis." (PMID 34977870, 2021). "Among the genes regulated by SAHA, CD36 low expression was associated with higher metastasis grade and poor prognosis in colon, breast, and ovarian cancers and pancreatic ductal adenocarcinoma." (PMID 34179011, 2021). "Both molecules can bind to collagen, and it has been shown that high expression of CD36 is associated with lower recurrence-free survival in ovarian cancer." (PMID 33352957, 2020). "Utilizing these FA-linked Pt (IV) prodrugs, it was demonstrated that increased CD36 expression in cisplatin-resistant ovarian cancer cells could be leveraged to overcome cisplatin resistance." (PMID 37371076, 2023). "In the previous reported, the CD36-driven omental adipocytes metabolic reprogramming and functions in tumor-associated immune cells lead to tumor immune tolerance and tumor development, especially in ovarian carcinomas." (PMID 36085041, 2022). "The over-expression of CD36, FATPs, and FABPs had been indicated in ovarian cancer and other malignancies, correlating to cancer proliferation and aggressive behavior including metastasis." (PMID 40709184, 2025). "Taken together, these studies illustrate that ovarian cancer promotes lipolysis and FAs uptake through transporters including CD36, FATPs, and FABPs, fueling tumor growth, metastasis, and drug resistance." (PMID 40709184, 2025). "Conversely, CD36 inhibition reduces migration, adhesion, and invasion in vitro, decreasing metastatic burden in xenograft models of ovarian cancer metastasis." (PMID 40136652, 2025). "CD36 expression is more frequent in visceral metastases than in normal ovarian tissue or primary ovarian cancer lesions." (PMID 40136652, 2025). "Therapeutically, targeting PSAP holds promise: a cyclic PSAP-derived peptide reactivates anti-tumor TSP-1/CD36 signaling to inhibit ovarian cancer growth and metastasis in vivo." (PMID 40801564, 2025). "The upregulation and prognostic relevance of CD36 in cancers have been reported in several entities, such as gastric cancer, colorectal cancer, ovarian cancer, prostate cancer, clear cell renal cancer, and squamous cancer." (PMID 39085485, 2024). "For example, in ovarian cancer, CD36 facilitates adaption and metastasis of tumor cells in adipocyte-rich TME." (PMID 37207149, 2023). "Cluster of differentiation 36 (CD36) is a cell surface scavenger receptor that plays critical roles in many different types of cancer, notably breast, brain, and ovarian cancers." (PMID 37371076, 2023). "It was initially demonstrated that a peptide derived from the glycoprotein prosaposin can induce CD36-mediated apoptosis in ovarian cancer via promoting TSP-1 expression in bone marrow-derived cells." (PMID 37371076, 2023). "Adipocytes from human greater omentum can induce the expression of CD36 in ovarian cancer cells, which is a unique feature distinguishing it from other omental cell types, including fibroblasts and macrophages." (PMID 37605299, 2023). "The fatty acid receptor CD36 is highly expressed in peritoneal metastatic foci of ovarian cancer patients compared with orthotopic tumor sites." (PMID 36698173, 2023). "Although a few studies have reported that TSP-1-CD36-mediated apoptosis occurs in ovarian cancer and leukemia; this aspect of CD36 biology in cancer cells has remained largely unexplored and requires further study." (PMID 37371076, 2023).
ovarian carcinoma (continued). "SKOV3ip1 and OVCAR8 xenograft mouse models also indicate that CD36 regulates the metastasis of ovarian cancer." (PMID 37605299, 2023). "Other studies found that omental adipocytes had the ability to induce the expression of CD36 in neighboring ovarian cancer cells to facilitate the uptake of adipocyte-released FAs." (PMID 37371076, 2023). "We also showed that cisplatin induces the expression of HSP27 and FAO markers (i.e., CPT1A, CD36) in cisplatin-resistant ovarian cancer cells through ROS-dependent mechanisms as NAC treatment attenuates cisplatin induction of HSP27 and FAO." (PMID 37628819, 2023). "Conversely, CD36 inhibition reduced microenvironment-derived fatty acid uptake in ovarian cancer cells, decreasing adipocyte-stimulated invasion and migration in vitro, as well as tumor growth in vivo." (PMID 36670988, 2023). "A high CD36 expression level has also been described in cisplatin-resistant ovarian cancer cells and in leukemia stem cells exhibiting resistance to cytarabine and doxorubicin." (PMID 37371076, 2023). "Later, the same group observed that ovarian cancer cells cocultured with primary human omental adipocytes expressed high levels of CD36, thereby facilitating exogenous fatty acid uptake and ovarian cancer metastasis." (PMID 36670988, 2023). "Adipocytes were also shown to support ovarian cancer progression and metastasis by providing FA and the expression of CD36 on cancer cells." (PMID 35323656, 2022). "Adipocyte-ovarian cancer co-culture was demonstrated to express high levels of CD36, which coincided with an increased cellular FA uptake and lipid accumulation in ovarian cancer." (PMID 36428985, 2022). "In line with this, chemically inhibiting and ablating CD36 reduced the uptake of adipocyte-derived FA in ovarian cancer cells co-cultured with adipocytes, inhibiting tumorigenic potential and metastasis." (PMID 35448537, 2022). "Ovarian cancer cells co-cultured with primary human omental adipocytes have a high expression level of the fatty acid receptor CD36 in the plasma membrane, which facilitates exogenous fatty acid uptake." (PMID 35634242, 2022). "Ovarian cancer cells expressed high CD36 levels when co-cultured with primary human omental-derived adipocytes, resulting in increased FA uptake." (PMID 35625629, 2022). "Co-culture of ovarian cancer cells with omental adipocytes upregulated CD36 expression and accelerated FFA uptake in cancer cells." (PMID 34888248, 2021). "For instance, CD36 is significantly upregulated in malignant epidermal tumor cells such as ovarian cancer and gastric cancer, and is correlated with metastasis and poor prognosis for patients." (PMID 34888248, 2021). "ADI have also been reported to induce CD36 on ovarian cancer cells allowing for the uptake of fatty acids and the formation of lipid droplets, thereby contributing to peritoneal metastasis." (PMID 34841720, 2021). "In several carcinoma, such as breast cancer, ovarian cancer and pancreatic cancer, CD36 drives the progression of cancer cells." (PMID 34439279, 2021). "CD36 overexpression is induced by co-culture of adipocytes and ovarian cancer cell lines and promotes fatty acid uptake." (PMID 33499022, 2021). "Increased lipid uptake regulated by the receptor CD36 and the transport protein FABP4 has been implicated in ovarian cancer metastasis." (PMID 31769430, 2019). "The authors found that human primary adipocytes induced CD36 mRNA level and plasma membrane expression in co-cultured ovarian cancer cells." (PMID 31769430, 2019). "Induction of adipocyte CD36 expression results in enhanced ovarian cancer progression and metastasis and drives glioblastoma progression." (PMID 30573731, 2018). "Studies have reported that patients with advanced stage ovarian cancer showed upregulated CD36 expression and that inhibition of CD36 reduced tumor growth and metastasis." (PMID 29914089, 2018).
ovarian carcinoma (continued). "However, it has also been reported that ovarian cancer cells cocultured with adipocytes express high levels of CD36 and that the inhibition of CD36 attenuated adipocyte-induced lipid droplet accumulation and reduced the ROS content." (PMID 41285714, 2025). "Omental adipocytes induce CD36 expression in ovarian cancer cells, promoting FFA uptake." (PMID 40136652, 2025). "Therefore, these researches demonstrate that CAAs promote tumor progression by releasing FAs (via CD36/FABPs) to fuel ovarian cancer cell growth, metastasis, and chemoresistance through enhanced FAO." (PMID 40709184, 2025). "Moreover, co-culture studies have revealed that omental adipocytes can induce the expression of CD36 in ovarian cancer cells to facilitate the uptake of adipocyte-derived FAs into cancer cells, promoting tumor growth and enhancing metastasis." (PMID 37371076, 2023). "All these facts indicate that omental adipocytes can alter ovarian cancer metabolism by CD36; they can not only promote exogenous lipid uptake rather than endogenous lipid synthesis but also enhance anaerobic glucose metabolism while suppressing glucose oxidation." (PMID 37605299, 2023). "Moreover, adipocytes promote fatty acid uptake and energy metabolism in ovarian cancer cells by upregulating CD36 expression on the surface of ovarian cancer cells, resulting in peritoneal metastasis of the tumor." (PMID 36698173, 2023). "Furthermore, in vitro experiments, CyQuant cell proliferation assays and transwell assays showed that CD36 can promote ovarian cancer cell proliferation, invasion and migration." (PMID 37605299, 2023). "Despite its initial promise as a CD36 inhibitor to treat ovarian cancer, it was thereafter abandoned, as phase II clinical trials of ABT510 treatment in advanced renal cell carcinoma, soft tissue sarcoma and metastatic melanoma showed it lacked sufficient clinical efficiency." (PMID 35448537, 2022). "Interestingly, in an ovarian cancer model, it has been demonstrated that CD36 expression is increased by omental adipocyte proximity and its expression in metastasis-initiating cells is associated with metastasis dissemination and poor prognosis." (PMID 34359819, 2021). "In addition, CD36 plays a role in multiple processes of ovarian cancer metastasis to the omentum, including adhesion, invasion, migration and non-anchored growth." (PMID 33926551, 2021). "This is consistent with recent data obtained from the ID8 ovarian carcinoma model in which gene therapy vectors engineered to express 3TSR (i.e., CD36-activating TSP-1 fragment), together with a CD47-binding peptide, were shown to inhibit primary tumor growth and development of secondary lesions." (PMID 34638503, 2021). "Another study found that in a coculture model consisting of adipocytes and ovarian cancer cells, the expression of the fatty acid receptor CD36 on the membrane of the ovarian cancer cells is increased, promoting the uptake of fatty acids by ovarian cancer cells." (PMID 33926551, 2021). "Thus, CD36 inhibition can effectively reduce fat acid uptake from microenvironment in ovarian cancer cells to suppress adipocyte-mediated tumor progression." (PMID 33194756, 2020). "Studies have found that CD36 is highly expressed in ovarian cancer tissues and also metastatic tissues, which shows that CD36 may participate in the metastasis and proliferation of ovarian cancer." (PMID 33194756, 2020). "However, some studies used CD36 as a therapeutic escape for Cisplatin-resistant ovarian cancer." (PMID 38370376, 2024). "For instance, the activation of NF-κB could trigger lipid metabolic rewiring in ovarian cancer cells, thereby activating a transcriptional program that leads to increased CD36 expression, which in turn can be critical for ovarian cancer survival and metastasis." (PMID 37371076, 2023). "Thus, it has been proposed that inhibiting CD36 could be an effective treatment strategy against ovarian cancer metastasis." (PMID 35634242, 2022).